DEFB108C (defensin beta 108C)
Description:
Has antibacterial activity.
Synonyms: formerly DEFB108P2
Gene: Protein-coding gene on chromosome 8 (7,373,114 to 7,377,500, forward strand). Ensembl gene ENSG00000215371.
Subcellular location: Secreted
Homologues: Orthologues: macaque DEFB108B (82% identical), mouse Defb22 (17% identical), rat Defb22 (14% identical). Paralogues in human: DEFB108B (83% identical), DEFB116 (25% identical), DEFB118 (24% identical), DEFB132 (24% identical), DEFB104A (23% identical), DEFB104B (23% identical), DEFB115 (23% identical), DEFB135 (23% identical), DEFB121 (22% identical), DEFB123 (22% identical), DEFB127 (22% identical), DEFB129 (22% identical), and 7 more.